BCL3 (BCL3 transcription coactivator)
Diseases named in the same sentence as BCL3 in open-access papers (continued):
Sharing a sentence is not in itself a finding about the gene and the disease.
viral encephalitis (1 paper, 2023). Encephalitis resulting from viral infection. "Li found that the ceRNA pathways of circ_0000220, miR-326-3p and BCL3/MK2/TRIM25 played roles in viral encephalitis, demonstrating that viral encephalitis caused by JEV infection is regulated by a complex ceRNA network." (PMID 38249464, 2023). "JEV infection of mouse brain tissue can cause significant changes in circRNA_0000220 and the downstream targets of circRNA_0000220, i.e., miR-326-3p and BCL3/MK2/TRIM25, ultimately affecting the occurrence of viral encephalitis." (PMID 38249464, 2023).
cancer (83 papers, 2006 to 2025). A tumor composed of atypical neoplastic, often pleomorphic cells that invade other tissues. "Overexpressed, mutated and/or phosphorylated Bcl3 has been implicated in several cancers due to its altered transcriptional activities." (PMID 41439955, 2025). "In our previous human patient studies, we also proposed that Bcl-3 expression and localization can be used as a diagnostic marker in different types of cancer." (PMID 38238702, 2024). "BCL3 has been implicated in most of the hallmarks of cancer and as a modifier of disease progression and drug resistance impacts directly on key areas of clinical unmet need." (PMID 38195591, 2024). "It has been previously established in breast and other cancer types that Bcl3 loss can sensitise tumour cells to exogenous stress such as DNA-damaging agents." (PMID 38255248, 2024). "Below, we summarise the evidence demonstrating causative roles for BCL3 in each of these cancer related hallmarks." (PMID 38195591, 2024). "The weight of evidence determines that BCL3 is a multifaceted regulator of key cancer pathways associated with many of the hallmarks of cancer." (PMID 38195591, 2024). "Bcl-3 expression and function have been associated with the promotion of stemness in both normal and cancer cells." (PMID 35681213, 2022). "Here, we summarize the current understanding of BCL-3 function in relation to the characteristics or traits associated with tumourigenesis, termed ‘Hallmarks of Cancer’." (PMID 31930327, 2020). "Bcl3 was first identified as a putative proto-oncogene and while overexpression has been associated with some cancer types, BCL-3 also has an critical role in limiting NF-κB transcriptional activity in immune cells and promoting endotoxin tolerance to LPS." (PMID 27187478, 2016). "Since Bcl-3 has been implicated in abnormal cell survival we next asked if Bcl-3 is required for the survival of HCT116 cancer cells." (PMID 19806201, 2009). "It has been suggested that other cancer types may become ‘addicted’ to Bcl3 and that a loss of Bcl3 can specifically disrupt tumour cell survival, further adding to the appeal of targeting Bcl3 therapeutically." (PMID 38255248, 2024). "In addition to the regulation of apoptosis, the protein products of these genes are involved in signaling pathways that are associated with cancer development and progression, including NF-ĸB (BCL3, SPHK1, and PRKCZ) and c-MYC (PIM1 and BTG1)." (PMID 38731835, 2024). "In addition to earlier studies on anti-estrogen resistance and the effect of cancer-associated fibroblasts, we initially investigated the BCL3 expression in our model for acquired tamoxifen resistance." (PMID 35020071, 2022). "In contrast to cancer cells, either upregulation or downregulation of Regnase-1 in primary-culture chondrocytes via infection of Ad-Regnase-1 and Ad-shRegnase-1, respectively, did not modulate the mRNA levels of apoptosis-associated Fas, Bad, or Bcl3." (PMID 33853646, 2021). "In addition to the diagnostic value of BCL3 in cancers, prognostic value of BCL3 remains controversial in human cancers." (PMID 30357752, 2019). "Thus JNK-2 silencing in HCT116 cancer cells causes down-regulation of Bcl-3 expression and this effect is mediated via c-Jun." (PMID 19806201, 2009). "Moreover BCL3 has been implicated in TNF-alpha mediated signaling via stabilisation of RIP1 through CYLD ubiquitination in non-cancer cells suggesting that it may also have a role in TNF-alpha responses in the local microenvironment." (PMID 38195591, 2024). "Studies on cancers from various origins have proven that increased BCL3 expression leads to aggressive tumour behaviour, reinforcing the notion of BCL3-mediated immunological changes as a possible driver of OC disease progression." (PMID 40486320, 2025).
cancer (continued). "The results from this research confirm this mechanism through patient data, where higher BCL3 expression was predominantly observed in Stage III and Stage IV tumour cases, suggesting that BCL3 supports aggressive cancer development." (PMID 40486320, 2025). "This work using a zebrafish model highlighted the protective and anti-inflammatory role of Bcl3, which is a complement to the mammalian findings where the overexpression of Bcl3 drives chronic inflammation and cancer progression." (PMID 41439955, 2025). "More recently, as other regulatory mechanisms have come to light, it has become clear that BCL3 impacts several of the ‘acquired capabilities’ and ‘enabling characteristics’ outlined as the key Hallmarks of Cancer." (PMID 38195591, 2024). "These more recent studies confirm that BCL3 plays a central role in modulating a network of cancer related transcription factors and other key oncogenic signals that enable hallmarks of cancer and modulate cancer progression." (PMID 38195591, 2024). "This is supported by studies reporting specific micro-RNAs that target BCL3 to ameliorate cancer hallmarks." (PMID 38195591, 2024). "High expression of the proto-oncogene Bcl-3 promotes the proliferation and metastasis of cancer cells originating from tissues such as the colon, prostate, breast, and skin." (PMID 38238702, 2024). "These initial proof of concept studies for the use of small molecule protein:protein inhibitors (PPIs) of BCL3 indicates the significant potential for these novel classes of BCL3 inhibitor as anti-cancer agents." (PMID 38195591, 2024). "This review has focused on the studies demonstrating direct effects of suppressing BCL3 activity on cancer progression and the majority of these have used BCL3-gene knockdown or knockout as the modality of BCL3 inhibition." (PMID 38195591, 2024). "Based on these discoveries, the overall aim of the present study was to discover, develop and characterize Bcl-3 inhibitors as anticancer drugs for human cancer patients." (PMID 38238702, 2024). "Each of the five transcription factor pathways regulated by BCL3 identified to date are canonical cell cycle related pathways in cancer." (PMID 38195591, 2024). "Studies of BCL3 using one or more of these cancer stem cell assays are less common, nonetheless two studies using models of CRC have demonstrated a role for BCL3 in promoting stemness in tumour cells." (PMID 38195591, 2024). "These pathways, commonly dysregulated in cancer, were notably more pronounced in individuals exhibiting elevated Bcl-3 expression compared to lower levels of Bcl-3." (PMID 39327470, 2024). "Bcl-3 has also recently been shown to promote a cancer stem cell phenotype in tumor cells, resistance to chemotherapy, and facilitation of tumor cell migration and invasion." (PMID 38238702, 2024). "Despite the overwhelming evidence supporting BCL3’s role as an oncogene and driver of disease progression, there have been two reports describing a protective role for BCL3 in specific cancer contexts." (PMID 38195591, 2024). "We also discuss promising novel combinatorial strategies in clinical trials targeting Bcl3, PD-L1 and IL-8 to increase the effectiveness of cancer immunotherapies." (PMID 39123403, 2024). "It remains to be determined if this reciprocal relationship exists in cancer cells, but it seems likely from the evidence to date that aberrant AKT signaling in cancer cells is impacted both by and on BCL3 activity." (PMID 38195591, 2024). "Future studies are likely to determine the full extent of BCL3’s role in cancer stemness across different tumour types." (PMID 38195591, 2024).
cancer (continued). "Despite these numerous associations with poor prognosis, the demonstration of a direct role for BCL3 as an oncogenic driver or disease modifier has only been demonstrated by experimentation in a handful of cancer types to date." (PMID 38195591, 2024). "Most of the early investigations into BCL3 function have since focused on its role in NF-kB mediated cell proliferation, inflammation/immunity and cancer." (PMID 38195591, 2024). "BCL3 mediates its effects through protein:protein interactions and disruption of these protein complexes have been shown to exhibit anti-cancer properties." (PMID 38195591, 2024). "With well evidenced roles in both primary tumour viability and progression to metastasis targeting BCL3 has potential to impact on long-term survival of patients in a number of cancer sub-types." (PMID 38195591, 2024). "BCL3 would be an attractive candidate for such an approach as the body of evidence (above) shows that a reduction in BCL3 expression has anti-cancer properties in a variety of contexts." (PMID 38195591, 2024). "Increased Bcl3 expression in cancer cells promotes their proliferation, migration, and metastatic potential, but the mechanisms that regulate the Bcl3 expression in solid tumors are incompletely understood." (PMID 37151134, 2023). "Since the increased expression of Bcl3 in cancer cells promotes their proliferation, migration, invasion, and metastases, Bcl3 has become an important target for development of anticancer strategies." (PMID 37151134, 2023). "In cancer, BCL-3 limits the impact of the enabling hallmarks of cell plasticity and tumor-promoting inflammation." (PMID 37736616, 2023). "At present, in addition to the work aimed at studying the molecular mechanism of Bcl-3, an increasing number of studies have focused on the effects of Bcl-3 on inflammation, immunity and malignant tumors in vivo." (PMID 35355979, 2022). "More recent work has demonstrated a further role for BCL-3 in cancer, promoting the stem cell phenotype in CRC, with implications for therapeutic resistance." (PMID 35468497, 2022). "In CRC, BCL-3 was shown to promote cancer cell growth and survival by phosphoinositide 3-kinase (PI3K) and mammalian target of rapamycin (MTOR) mediated activation of the AKT pathway." (PMID 35468497, 2022). "Noticeably, Bcl-3 in cancer cells mainly resides in the nucleus, while in hepatocytes, Bcl-3 is mostly expressed in the cytoplasm, suggesting that the function of Bcl-3 is cell-type specific." (PMID 34853447, 2022). "Long noncoding RNA LINC00176 positively upregulates the expression of ceruloplasmin by recruiting transcription factor BCL3, a proto-oncogene in cancer." (PMID 34413268, 2021). "First, we found that the expression of Bcl3 in normal mice roughly increased with prolonged cancer induction." (PMID 34530917, 2021). "Our results provide proof-of-principle for targeting Bcl-3 pharmacologically to optimize adaptive immune responses to infectious agents, cancer cells, vaccines and other stimuli that induce CD8+ T cell differentiation." (PMID 33508001, 2021). "In recent years there has been an increasing number of studies investigating the role of the atypical IκB protein BCL-3 in a wide range of human cancers; here we review its function in relation to the ‘Hallmarks of Cancer’." (PMID 31930327, 2020). "Given the emerging role of BCL-3 in a number of different cancers, we are hopeful that the new class of BCL-3 inhibitors currently under development will prove effective in a wide range of human cancers." (PMID 31930327, 2020).
cancer (continued). "These and other studies have begun to shed light on our mechanistic understanding of the function of BCL-3 in tumour promotion and progression, including the role BCL-3 plays in a number of the Hallmarks of Cancer." (PMID 31930327, 2020). "We suggest that BCL-3 represents an exciting new route for targeting the Hallmarks of Cancer; in particular by limiting the impact of the enabling hallmarks of tumour promoting inflammation and cell plasticity." (PMID 31930327, 2020). "As Bcl-3 is overexpressed in many human cancers and regulates stemness of colorectal CSCs, we considered a direct connection between Bcl-3 and the Wnt/β-catenin signaling pathways." (PMID 32355204, 2020). "We show that BCL-3 regulates β-catenin-mediated transcription and expression of colorectal stem cell and cancer stem cell (CSC) marker genes LGR5 and ASCL2, functionally promoting a stem cell phenotype in CRC cells." (PMID 30792270, 2019). "Previous reports suggested that PIR contributes to malignant transformation of cancer cells by acting as a transcriptional cofactor that interacts with the Bcl3–NF‐қB complex in several cancers." (PMID 30444038, 2019). "Bcl-3 expression has been described in a variety of cancer at different stages, including breast, nasopharyngeal and pancreatic cancer as well as lymphoma and HCC." (PMID 28915576, 2017). "To investigate the effects of Bcl-3 on pulmonary metastatic potential ofbreast cancer cells, we used in vitro systems to assess changes incell motility and invasion." (PMID 27906182, 2016). "Bcl-3 was highly expressed in malignantbreast cancer cell lines but undetectable in MCF-10A, a normal mammaryepithelial cell line." (PMID 27906182, 2016). "Nuclear localization of Bcl-3 has been reported as an indicator for cell proliferation in different types of cancer." (PMID 25929479, 2015). "Among the differentially expressed proteins, four factors (CNDP1, APOA4, DACH1 and BCL3) have previously been studied in different aspects of cancer, but only APOA4 and CNDP1 constitute secreted proteins." (PMID 25898255, 2015). "It has also been shown in a variety of cancer cells that basal apoptosis is suppressed by Bcl-3 in a regulatory loop induced by JNK1 and suppressed by the related JNK2." (PMID 22195643, 2011). "In conclusion, the present paper shows that the depletion of Bcl-3 in cancer cells induces centrosome amplification and increases ploidy." (PMID 20731879, 2010). "The involvement of Bcl-3 in the basal regulation of cancer cell survival versus apoptosis is particularly interesting, especially since Bcl-3 is already identified as a putative oncoprotein." (PMID 19806201, 2009). "Non-cancer ARPE19 cells showed different sub-cellular localisations compared with HCT116 cancer cells in that c-Jun and Bcl-3 proteins were localised in the nuclear soluble and insoluble fractions under basal conditions." (PMID 19806201, 2009). "Mechanistically this is attributable to JNK2-mediated suppression of c-Jun, which we identify as down-regulator of Bcl-3 expression in HCT116 cancer cells." (PMID 19806201, 2009). "N4BP2 is a Bcl-3 binding protein, and Bcl-3 is an oncoprotein that is overexpressed in certain cancers, including NPC." (PMID 17626640, 2007). "Clonogenicity, here defined as the ability for single cancer cells to generate a new colony of cells in vitro (e.g. colony formation assay) has been shown to be inhibited following suppression of BCL3 in a number of tumour types, including gastric, colorectal, breast, cervical and ovarian." (PMID 38195591, 2024). "Whether these modifications which include phosphorylation and ubiquitination could be harnessed directly or through targeting of BCL3 upstream modifiers, as suggested for the cancer related deubiquitination enzyme CYLD, remains to be determined." (PMID 38195591, 2024). "Increased levels of Bcl-3 in these cancer forms correlated with poor prognoses of patients." (PMID 38238702, 2024).